APOE (apolipoprotein E)
Diseases named in the same sentence as APOE in open-access papers (continued):
Sharing a sentence is not in itself a finding about the gene and the disease.
cognitive decline (continued). "While our numbers are small, a much larger study of 219 people reported that 65.3% had cognitive decline post infection, and of those, 30.6% had the APOE e4 allele versus 16.4% for the cognitively normal group." (PMID 41369364, 2025). "The clear associations between APOE ε4 and AD has led to numerous investigations attempting to examine its potential role as a biomarker of cognitive decline in PD and the occurrence of PDD." (PMID 41180817, 2025). "Despite the well-documented link between APOE ε4 and cognitive decline, the interactions between this genetic risk factor and cardiometabolic health conditions across population prevalence racial ethnic backgrounds remain poorly understood." (PMID 41035086, 2025). "The cognition of APOE4 carriers dramatically worsens in the presence of CVDs and APOE4 carriers demonstrate faster cognitive decline than other APOE variants." (PMID 39766777, 2024). "Compared with other APOE alleles, APOE ε4 carriers showed a higher risk of developing sporadic AD, earlier onset age, higher rate of cognitive decline, and poorer cognitive function." (PMID 37697966, 2024). "On the other hand, SCD-ɛ4 older adults had increased rates of cognitive change compared to both NC-ɛ4 and MCI-ɛ4, indicating that early in the decline process, APOE status is strongly associated with rate of cognitive decline, more than in someone with MCI." (PMID 38253819, 2024). "This reinforces the notion that female patients with temporal lobe epilepsy and the APOE ε4 allele are at an increased risk for both cognitive decline and depression." (PMID 39886338, 2024). "The APOE ε4 allele has been associated with cognitive decline, abnormal levels of amyloid and tau proteins, cortical atrophy, disruption of the cerebral white matter in neuroimaging and functional brain network changes in individuals with SCD." (PMID 38534745, 2024). "Our previous study has found that aging, increased activity of GSK-3β, the presence of ApoE ε4 genotype, and olfactory dysfunction are associated with cognitive decline in T2DM patients." (PMID 38660514, 2024). "A more recent study tested the interaction between APOE genotypes and air pollution and found that the long-term exposure to ambient air pollution was associated with a more rapid cognitive decline in APOE4 carriers." (PMID 39135618, 2024). "These analyses underscore the importance of considering sex and APOE-ε4 status in testosterone and brain health studies, and posits potential for modifiable risk factors for cognitive decline, particularly among women at higher genetic risk for AD." (PMID 38835072, 2024). "APOE ε4 allele variant, associated with late‐onset Alzheimer's and cognitive decline—increase in allele frequency by age." (PMID 38359178, 2024). "Several studies have focused on the association between APOE ε4 and cognitive decline in healthy individuals during early life." (PMID 38605018, 2024). "Further evidence is needed in order to clarify if there is a synergistic interaction between apathy and the APOE e4 allele in affecting the risk of cognitive decline." (PMID 38473892, 2024). "Our results suggest that brain atrophy with DIR GMV and cognitive decline with aging can be useful biomarkers for predicting ApoE ε4 status and identifying individuals at risk of AD progression." (PMID 38376028, 2024). "Association of the APOE ε4 allele with cognitive decline in AD has been reported with some discrepancies due to the diversity of methods utilized for assessing cognition and intrinsic genetic and demographic variability in the analyzed populations." (PMID 39337715, 2024). "In the context of AD, the focus should be on individuals at risk, such as those with MCI, subjective cognitive decline, elders with positive Aβ or tau biomarkers, APOE-ε4-carriers or healthy elderly individuals with high-risk scores." (PMID 39501255, 2024).
cognitive decline (continued). "Cognitively normal APOE ε4 carriers with high CSF ferritin have increased risk of cognitive decline compared to non-ε4 carriers, and in another cohort, the odds ratio for CSF ferritin in predicting AD diagnosis was higher in ε4 subjects." (PMID 35484240, 2024). "Previous research showed that young APOE e4 carriers show higher wayfinding distances in virtual spatial navigation tasks (e.g., Couglan and colleagues) and APOE e4 status has also been linked to an increased subjective perception of cognitive decline." (PMID 39361552, 2024). "Previous studies generally show that APOE is more likely to modulate risk for neurodegeneration in women resulting in faster cognitive decline in the presence of amyloidosis." (PMID 38230720, 2024). "More specifically, among carriers of at least one APOE e4 allele, psychosis was related to a greater hazard for cognitive decline, and a significant interaction was also observed between psychosis and APOE allele status." (PMID 38473892, 2024). "In a longitudinal study, individuals with both BDNF Met and APOE E4 alleles exhibited more pronounced entorhinal cortex atrophy and cognitive decline over three years compared to Val/Val homozygotes in cases of mild cognitive impairment (MCI) and AD." (PMID 38916728, 2024). "The Ketogenic, Mediterranean, and MIND diets emerged as key dietary patterns for cognitive decline prevention, highlighting the role of genetic factors, especially ApoE polymorphisms, in cognitive deterioration." (PMID 38803449, 2024). "ApoE ε4 carriers have a higher risk of developing AD and show cognitive decline even before diagnosis." (PMID 38376028, 2024). "For instance, increased physical activity has been shown to attenuate the vulnerability associated with the apolipoprotein E ε4 (APOE ε4) allele to early cognitive decline in patients with PD." (PMID 39767666, 2024). "On follow-up, age, male sex, unskilled work, polypharmacy and Apolipoprotein E allele 4 (APOE ε4) were longitudinal risk factors for cognitive decline." (PMID 38824519, 2024). "Our previous multicenter case-control study showed that aging, up-regulation of platelet glycogen synthase kinase-3β (GSK-3β), impaired olfactory function, and ApoE ε4 genotype were associated with cognitive decline in type 2 diabetes mellitus (T2DM) patients." (PMID 38660514, 2024). "The Apolipoprotein E (APOE) gene in humans is a major risk factor for cognitive decline in aging, with the APOE4 allele conferring risk compared to APOE369." (PMID 37758709, 2023). "The group experiencing cognitive decline exhibited a higher prevalence of the APOE ε4 allele than the normal group (30.8% vs. 16.4%, respectively, p = 0.038)." (PMID 38137059, 2023). "This supports our finding that APOE-ε4 increases the risk of cognitive decline, however we also found a significant association between APOE-ε4 and dual decline." (PMID 36891556, 2023). "The group experiencing cognitive decline exhibited a higher frequency of the APOE ε4 allele than the normal group (30.8% vs. 16.4%, respectively, p = 0.038)." (PMID 38137059, 2023). "Our study simultaneously tested a panel of 27 immune markers and showed that IP-10, FGF-2, TGFa and VEGF concentrations in MCI patients were associated with APOE genotype, suggesting their association with cognitive decline in the elderly." (PMID 37686198, 2023). "The results reveal a positive association of ApoE ε4 with cognitive decline in T2DM patients, and a mediative role of GSK‐3β activation between the ApoE ε4 and cognitive impairment." (PMID 37700547, 2023). "Our results also showed that APOE-ε4 was a significant risk factor for cognitive decline and dual decline." (PMID 36891556, 2023). "Our study found a higher, statistically significant frequency of the APOE ε4 allele in the cognitive decline group than in the normal group, and the APOE ε4 allele was an independent risk factor for CD." (PMID 38137059, 2023).
cognitive decline (continued). "Baseline T lymphopenia even correlated with subsequent cognitive decline in Parkinson disease, but only in patients carrying the ApoE ε4 allele, an allele responsible for permeability of the blood brain barrier." (PMID 37954593, 2023). "Female sex, APOE-ε4 genotype and low education level have been identified as the biggest risk factors for cognitive decline, but their impact on early-stage structural alterations is not yet well understood." (PMID 37333001, 2023). "In another study, the strongest genetic risk factor for AD, APOE ε4, was found to potentially modulate the association between hypertension and cognitive decline." (PMID 38062190, 2023). "Understanding the multiple mechanisms through which age and gender interact with ApoE alleles to influence cognitive function is crucial for developing personalized interventions and treatments for cognitive decline." (PMID 37700547, 2023). "For example, lower dynamic functional connectivity involving the insular and temporal neocortex was negatively correlated with the number of APOE ε4 alleles in patients with subjective cognitive decline." (PMID 36850008, 2023). "Specifically, polymorphisms affecting the MAPT, COMT, GBA, and APOE genotypes have been linked to cognitive decline." (PMID 37885554, 2023). "Dual endpoints including TTE and a measure of cognitive decline perform better than the cognitive decline measure as a single primary endpoint in a cognitively unimpaired population at risk of AD (based on the APOE genotype)." (PMID 36879340, 2023). "AD progression and AD patients’ cognitive decline has been shown to be largely influenced by positivity for the ε4 allele of the apolipoprotein E gene (APOE4)." (PMID 37358619, 2023). "In one study, the association between velocity of cognitive decline and different nutrient patterns varied depending on the APOE ε4 genotype." (PMID 36152054, 2023). "APOE-ε4 enhanced the burden of oligomeric β-amyloid at the synapse, which in turn is associated with synapse shrinking and loss, a known cause of the cognitive decline in AD." (PMID 38115150, 2023). "The most common blood tests were blood tests to rule out other causes of cognitive symptoms (i.e., treatable causes of cognitive decline, such as vitamin B12 deficiency; 40.5%), followed by genetic tests for APOE ɛ4 or other relevant mutations (19.8%)." (PMID 37483324, 2023). "For example, it has been proposed that carrying at least one copy of the APOE ε4 allele impairs the astroglial response to Aβ plaques, which is in turn correlated to cognitive decline." (PMID 36614219, 2023). "The APOE e2 allele has also been associated with delayed onset and protection against cognitive decline in older adults." (PMID 37612284, 2023). "For example, the apolipoprotein E (APOE) ε4 allele is one of the most significant risk factors for cognitive impairment, accounting for about 5% of the variance in lifetime cognitive decline." (PMID 38161596, 2023). "Several studies have reported an association between APOE ε4 status and cognitive impairment in individuals with PD, indicating its potential role as a genetic risk factor for the development of cognitive decline in these patients." (PMID 38026513, 2023). "Apolipoprotein E (APOE) ε4 homozygosity, a strong risk factor for AD, was also suggested a potent predictor of cognitive decline in patients with early relapse-remitting MS." (PMID 37397465, 2023). "A major risk factor for AD is the presence of the APOE ε4 allele; however, few studies have simultaneously investigated its role with respect to cognitive decline, specifically logical memory." (PMID 37834863, 2023). "By applying multivariate regression, the odds ratio (OR) of cognitive decline for carrying any ApoE ε4 allele was 1.89 in contrast to the ε3/ε3 polymorphism." (PMID 36578446, 2022).
cognitive decline (continued). "The pathophysiologic basis for APOE ε4 and ε2 as risk and protective factors, respectively, for cognitive decline in neurodegenerative disorders have yet to be clearly elucidated although clues to biologically plausible mechanism are emerging." (PMID 36371506, 2022). "Regardless, our findings suggest that associations of CRARs (i.e., weaker rhythm strength) and cognitive decline are more robust among APOE e4 carriers." (PMID 36312032, 2022). "Combining the genetic and clinical information, we detected cognitive decline and optimize interventions early when the patients present a specific illness in a particular age and carry a specific ApoE allele." (PMID 36578446, 2022). "One of the risk factors for developing cognitive decline is Apolipoprotein E E4 (APOE4), and a high blood ascorbic acid level correlates with a reduction of APOE4 associated cognitive decline." (PMID 35955833, 2022). "It is well recognized that individuals carrying the ApoE ε4 allele are at high risk for cognitive decline and AD." (PMID 35517054, 2022). "Presence of APOE ε4 is associated with an increased risk of cognitive decline and AD and is an important measurement to build predictive models." (PMID 36295851, 2022). "Studies using longitudinal designs in this clinical population are thus needed to characterize the trajectory of WMH volume changes in relation to age, cognitive decline, and other well-defined disease risk factors (e.g., APOE ε4 genotype)." (PMID 35768838, 2022). "We now additionally show that in survival analyses the brain age residual was associated with cognitive decline even after adjusting for baseline age, amyloid, and APOE e4 status." (PMID 35974140, 2022). "But rs429358-C, a coding apolipoprotein E (APOE) SNP and one of the variants previously associated with cognitive decline, was associated with general cognitive decline in our study as well (p-value = 1 × 10−5, Beta = −0.013)." (PMID 36446774, 2022). "The ApoE allele variation is implicated in many common illnesses including cognitive decline measured by MMSE and AD, and there is a synergistic effect between ApoE4 carrier status and cognitive status in relation to mortality." (PMID 36518570, 2022). "Our study demonstrates that high OCRS is associated with a reduced association of APOE-ε4 and AD biomarkers with cognitive decline and memory function, respectively." (PMID 36571008, 2022). "Significant interactions suggest that CRARs are generally more strongly associated with cognitive performance and rate of cognitive decline among women, Black adults, older individuals, and APOE e4 carriers." (PMID 36312032, 2022). "The ε4 allele of the apolipoprotein E (APOE) gene is a strong genetic risk factor for aging-related cognitive decline." (PMID 35847686, 2022). "For instance, CR and BR concepts would make identical predictions about the association of APOE-ε4 with cognitive decline, despite different underlying mechanisms." (PMID 36571008, 2022). "Sensitivity analyses excluding APOE showed slightly older ages of divergence, suggesting that, as expected, APOE ε4 allele carriers experience earlier cognitive decline." (PMID 35377426, 2022). "Our results suggest that ApoE rs429358 variant reveal unsusceptible to cognitive decline, while ApoE rs7412 variant imply its unfavourable influence on cognitive function in these older Chinese adults, independently of tHcy levels." (PMID 35351068, 2022). "The conjunction of APOE ε4 genotype and hypercholesterolemia has been associated with even greater cognitive decline than either risk factor alone." (PMID 35404972, 2022). "The AD-RAI can predict the risk of progression to AD in people with MCI carrying APOE ε4, is strongly correlated with cognition, and can predict cognitive decline." (PMID 35572149, 2022). "Our result for the longitudinal association between rs429358 in the APOE coding region and cognitive decline is in line with the three GWASs on cognitive decline." (PMID 36446774, 2022).
cognitive decline (continued). "Nevertheless, these findings suggest that KL-VSHET+ exerts an APOE ε4-genotype dependent protective effect on CSF Tau and pTau concentrations and on subsequent cognitive decline in older cognitively normal participants susceptible to AD." (PMID 35617280, 2022). "Combining the genetic and clinical information, we have the odds to early detect cognitive decline and optimize interventions when the subjects first present with a specific illness at a particular age and carry a specific ApoE allele." (PMID 36578446, 2022). "In mild cognitive impairment (MCI) cases, BCHE-K and APOE-4 accelerate cognitive decline, hippocampal volumetric loss, and progression to AD." (PMID 35330211, 2022). "Our study suggests that AD pathology and cognitive decline are associated with increased plasma IgA levels in an APOE allele-dependent manner, where the associations are lost in APOEε4 carriers." (PMID 36008818, 2022). "As the most prevalent genetic risk factor for AD, apolipoprotein E4 (apoE4) has been identified to trigger apoptosis, leading to a series of detrimental consequences such as impaired neuroplasticity and cognitive decline." (PMID 35096262, 2022). "In conclusion, our results suggest that APOE ε4 carriers are at increased risk for cognitive decline and abnormal FC in the left FP network if they suffer from hypertension as well." (PMID 35624902, 2022). "Studies including GWAS of neuropathologically confirmed PD have also strengthened the credibility of an association with APOE e4 carrier status by demonstrating a significant association with cognitive decline in PD25,26." (PMID 36371506, 2022). "The aim of our study was to investigate association between COVID-19 infection and APOE genotype as factors contributing to cognitive decline in older adults with a follow-up period of 1 year." (PMID 36292001, 2022). "Third, a SNP within the APOE region was included in the computation of GRS-AD and limits the interpretation of GRS-AD other than APOE4, which are known to increase the risk of cognitive decline in PD5,32,33." (PMID 35545633, 2022). "So far, increased Aβ oligomer levels were especially observed for APOE ε4 allele carriers and have been associated with an accelerated memory impairment, as well as early cognitive decline." (PMID 35884866, 2022). "Regarding, higher OCRS was associated with a reduced association of APOE-ε4 with cognitive decline (mean follow-up = 6.03 years), consistent with CR and BR." (PMID 36571008, 2022). "Our results suggested that APOE ε4 risk genes target a specific pattern of cognitive decline and FC changes and elevate frontoparietal dysfunction in hypertensive patients." (PMID 35624902, 2022). "The findings from the reviewed article suggested that in AD patients, the L variant is associated with higher AD risk and increased cognitive decline in APOE e4 carriers." (PMID 35964003, 2022). "A recent study has indicated that APOE ε4-associated breakdown of the blood-brain barrier in the hippocampus and medial temporal lobe contributes to APOE ε4-associated cognitive decline independently of Aβ or tau." (PMID 33397400, 2021). "That the APOE-ε4 allele is important in predicting pathological cognitive decline was shown in the Nun study, where the APOE-ε4 allele was found to be a relevant predictor in the transition from unimpaired to mildly impaired cognitive abilities." (PMID 34786016, 2021). "- Engagement in leisure activities is associated with a lower risk of cognitive decline, while carriage of an APOE ε4 allele is associated with faster cognitive decline." (PMID 34616288, 2021). "Longitudinal studies have found associations with APOE ε4 and a more rapid cognitive decline measured on both screening instruments for global cognition and battery-style assessment of mental status." (PMID 33613437, 2021). "Analyses of general cognitive decline in the wider setting of older adults have most consistently implicated variants in the APOE region on chromosome 19." (PMID 33757599, 2021).